DCN (decorin)
Diseases named in the same sentence as DCN in open-access papers (continued):
Sharing a sentence is not in itself a finding about the gene and the disease.
cancer (continued). "Another myokine that may have anti-cancer potential is decorin, ubiquitously expressed in connective tissues." (PMID 38067295, 2023). "In this study, we discovered that B.adolescentis suppressed colorectal tumorigenesis through inducing DCN+ macrophages, and targeting macrophages with B.adolescentis maybe a potential novel strategy for cancer therapy." (PMID 37464382, 2023). "Important proteoglycans that are upregulated in cancer include syndecans, glypicans, perlecans, agrins, small leucine-rich proteoglycans (SLRPs) such as biglycans, lumicans, and decorin." (PMID 36693448, 2023). "Similarly, fibroblast-like cancer cells (C10) and endothelial cell-like cancer cells (C11) were identified based on the specific expression of fibroblast markers (DCN, COL1A2 and COL6A3) and endothelial cell markers (PCAT19, VWF and PLVAP)." (PMID 36451812, 2022). "Stromal cells (or cancer-associated cells) included endothelial cells (PECAM1/CD31+ and MMRN1+), fibroblasts (COL6A1+, COL1A1+, THY1+, and DCN+), epithelial cells (LAMC2+, KRT5+, and KRT14+), and unassigned name cells (high heat shock proteins expression), suggesting that they were cancerous cells." (PMID 35742914, 2022). "It has been shown that the expression of DCN is reduced in many carcinomas, e.g., in the ovaries, lung, oesophagus and others, where DCN is mainly synthesised by stromal cells, whereas it is almost completely absent in tumorous cells or rarely by actively dividing normal cells." (PMID 35052821, 2022). "However, in the context of cancer progression, TGFβ was the first growth factor with which DCN was identified to interact." (PMID 34379688, 2021). "In carcinogenesis, decorin could promote the development of cancer as a pan tyrosine kinase inhibitor." (PMID 34987579, 2021). "The antagonistic effect of decorin on Met signaling results in down-regulation of the major oncogene β-catenin and its downstream effector MYC (myelocytomatosis oncogene protein), both involved in the pathologies of various cancers, and thus promotes an anti-tumorigenic activity of decorin." (PMID 34917515, 2021). "Decorin exhibits inhibitory effects in tumorigenesis in various types of cancers." (PMID 34386415, 2021). "Decorin is found to exhibit inhibitory effects in tumorigenesis in various types of cancers." (PMID 34386415, 2021). "Decorin functions in the tumorigenesis of various types of cancer." (PMID 34504839, 2021). "The expression of DCN gene in cancer tissues was lower than that in para-cancerous tissues." (PMID 32714651, 2020). "The ability of decorin to differentially regulate the cell proliferation is well known for many years and the anti-proliferative effects of decorin are considered to be involved in its anti-cancer effects." (PMID 32731559, 2020). "DCN plays multiple roles in soft tissue physiology and cancer progression." (PMID 33317052, 2020). "Indeed, a dichotomy of decorin effects on IGF-IR signaling was identified in normal as compared to cancer tissues." (PMID 32847060, 2020). "Currently, decorin is considered a potential therapeutic target for both cachexia and cancer." (PMID 32443765, 2020). "Therefore, decorin presumably plays a crucial role in counteracting the Warburg-effect in the metabolism of cancer cells, but further clarification and discussion remains for future studies." (PMID 32824864, 2020). "Our results suggest the idea that decorin can be utilized as an anti-cancer agent." (PMID 32477937, 2020). "Decorin suppresses cancer cell growth by blockade of cancer cell TGF-beta signaling." (PMID 30813947, 2019). "Thus, the mentioned genetic and preclinical discoveries highlight DCN as a promising and viable anti-cancer target for some types of cancer." (PMID 29435195, 2018). "We observed that DCN expression induced potent inhibition of cancer cell proliferation." (PMID 29100340, 2017).
cancer (continued). "In addition to its prominent role as an ECM regulator, DCN also serves as a key signaling molecule that suppresses cancer cell growth, inhibits metastasis, and induces apoptosis in cancer cells." (PMID 29100340, 2017). "Other studies have also suggested that DCN expression induced cancer cell killing and apoptosis." (PMID 29100340, 2017). "Moreover, in Ad-DCN transduced explant cultures, residual rounded cancer cells with hyperchromatic nuclei were distributed in clusters and also areas of cell debris were clearly detected." (PMID 28653173, 2017). "Also the proliferation index of cancer tissue was statistically significantly decreased in response to Ad-DCN transduction." (PMID 28653173, 2017). "This has led to the speculation that degradation of decorin may induce the development of cancer and fibrotic diseases by disrupting the binding to its binding partners." (PMID 28793886, 2017). "Lately, the role of decorin in the regulation of cancer cell mitophagy has gained attention." (PMID 28653173, 2017). "Furthermore, DCN tends to bind and downregulate several different receptor tyrosine kinases (RTKs), which are often overexpressed in cancer cells." (PMID 29100340, 2017). "DCN is of great importance as a major component in both extracellular and intracellular matrix and plays critical roles in the pathogenesis of certain human diseases and disorders, especially in various types of cancers." (PMID 27398310, 2016). "Decorin reportedly augments the expression of MMP-9 in cancer cell lines." (PMID 25781946, 2015). "Furthermore, the fusion of CAR to recombinant DCN further enhances its neutralization of TGF-β stimulated cancer cell proliferation and spreading significantly." (PMID 26697491, 2015). "In addition to paracrine regulation of stromal protein expression, we aimed to investigate the effects of decorin on cancer cell adhesion." (PMID 25593993, 2014). "Indeed, decorin gene expression in healthy human breast tissue as well as in benign and malignant tumors of human breast was shown to take place solely in cells of the original stroma." (PMID 23007289, 2013). "If this is the case, then the choice of the stromal-decorin and stromal-laminin sets could be justified by their potential roles as indicators of the aberrant state of at least two cell types within the cancer-affected tissue." (PMID 22719844, 2012). "In addition, the strong ubiquitous DCN stroma staining makes it difficult to evaluate DCN epithelial staining in some invasive cancers with a single-cell invasive pattern." (PMID 22363530, 2012). "Simultaneously, decorin induces the expression of several tumor suppressor genes that, like several of the downregulated targets, have never previously been linked to cancer progression." (PMID 23029096, 2012). "Accordingly, any mechanism that would boost endogenous expression of decorin or any therapeutic modality that could efficiently and specifically deliver decorin to carcinomas could represent a novel therapeutic choice against cancer." (PMID 23029096, 2012).
cancer (continued). "However studies by us and others have demonstrated that there are exceptions to this prevailing decorin expression and decorin mediated growth suppression model in cancer." (PMID 21958730, 2011). "DCN expression levels were analyzed in 29 effusions and 35 primary carcinomas using qRT-PCR." (PMID 19680458, 2010). "In addition, our comparative analysis revealed that CAFs and pericytes could be clearly distinguished in most cancers except HCC based on DCN (a CAF marker) and RGS5 (a pericyte marker)." (PMID 41228323, 2025). "The biological processes related to cancer development, signaling, and response comprised 12 distinct hallmark pathways enriched with genes related to hypoxia, including Enolase 1 (ENO1), Triosephosphate isomerase (TPI-1), Decorin (DEC) Fos- proto-oncogene gene (FOS), and Aldolase-(ALDO)." (PMID 39063015, 2024). "Moreover, SPARC and decorin might exert an anticancer effect by decreasing cancer cell proliferation, limiting migration and increasing apoptosis." (PMID 37533033, 2023). "Decorin could also target insulin-like growth factor 1 receptor (IGF1R) on the surface of cancer cells and inhibit its downstream signaling or target vascular endothelial growth factor receptor 2 (VEGFR2) on the surface of endothelial cells to promote autophagy." (PMID 36033387, 2022). "Therefore, decorin may induce autophagy in both cancer and inflammatory conditions, which, however, may need further studies to confirm." (PMID 36033387, 2022). "Since cancer-associated soluble factors such as inflammatory cytokines and IGF-1, or nutrition deprivation increased the plasma levels of DCN, the upregulation of DCN could reflect the chronic inflammation or metabolic dysfunction observed with cancer progression at least partially." (PMID 34884232, 2021). "Thus, we wanted to explore why was the anti-cancer gene, decorin, expressed highly in PC." (PMID 34021540, 2021). "However, whether decorin can induce this pathway in cancer cells that express converging signaling machinery is a point that needs to be further investigated." (PMID 32847060, 2020). "Furthermore, decorin also modulates cancer through its interaction with TGF-β." (PMID 31608236, 2019). "In addition, data have shown that osteoblasts naturally express decorin, implying that osteoblasts may naturally possess inhibitory effects toward metastatic cancer cells." (PMID 30813947, 2019). "Indeed, decorin is considered as a central modulatory molecule in various types of cancer." (PMID 28653173, 2017). "Thus, we used a TUNEL assay to investigate whether DCN mediates cancer cell killing via induction of apoptosis." (PMID 29100340, 2017). "Importantly, oncolytic Ad-mediated expression of DCN can emulate the strong apoptotic effect induced by conventional chemotherapeutics, making it a promising platform to supersede combination chemo/Ad therapy for the treatment of aggressive cancer." (PMID 29100340, 2017). "Interestingly, in spite of their pan-inhibitory properties against receptor tyrosine kinases (RTKs) and cancer growth pathways, the “guardian from the matrix” decorin (DCN) and lumican (LUM) SLRPs could exert anticancer effects in vivo and in vitro." (PMID 26230845, 2015). "In addition, we investigated the influence of decorin on cancer cell adhesion." (PMID 25593993, 2014). "In addition to its roles of modulating matrix assembly, fibrogenesis and cell proliferation, decorin displays anti-cancer activities through affecting signaling pathways of epidermal growth factor receptor (EGFR), transforming growth factor-beta (TGF-beta), and p21." (PMID 24625664, 2014). "Moreover, different types of human cancer cells could have different responses to decorin treatment, and different viral vector delivery methods could also lead to different proteome alterations." (PMID 24625664, 2014). "The interaction between DCN and TGF-β strongly inhibits the proliferation of different cancer cell lines." (PMID 40109852, 2025).
cancer (continued). "Despite this, they retained strong expression of core stromal markers such as DCN, VIM, LUM, and IGFBP7, which were consistently observed across both ex vivo and in situ fibroblasts compared to the epithelial cancer cells." (PMID 41198614, 2025). "Although both C1S and DCN dominantly mark CAFs alone, C1S was weakly detected in pericytes, but unexpectedly expressed in HCC cancer cells (C1S HCC)." (PMID 41228323, 2025). "There are over 600 myokines in human myocyte-conditioned medium, including myostatin, IL-6, IL-15, irisin, myonectin, decorin, SPARC and FSTL-1, some of which are involved in cancer suppression." (PMID 41300368, 2025). "Roles for decorin were reported via TGF-β modulation, showing inhibition of cancer growth, survival, metastasis and angiogenesis." (PMID 41300368, 2025). "We also included DCN and TGM2 because both are suggested to inhibit metastasis in different cancers by promoting cell–matrix interactions." (PMID 38598843, 2024). "In the W2 cluster, DEGs include POSTN, MFAP4, DCN, and LUM, which are closely involved in extracellular matrix organization as well as in cancer invasiveness." (PMID 39190696, 2024). "We identified a progenitor cell population highly enriched in samples from invasive and chemo-resistant carcinomas, characterized by a well-defined multigene signature including APOD, DCN, and LUM." (PMID 38466528, 2024). "We then screened 12 hub genes from the blue module based on MM and GS, such as PODN, DCN, CCDC80, SVEP1 and AEBP1, which were reported to be predictive biomarkers and correlated with immune infiltration in various cancers." (PMID 36768989, 2023). "The activation of mitophagy in cancer during the detachment from ECM depends on the expression of receptor-interacting protein kinase 1 (RIPK-1), and secretion of ECM protein decorin." (PMID 36906534, 2023). "It would therefore be of interest to study the utility of decorin and MCP-1 in this setting, not only in pancreatic but also in other types of cancer." (PMID 37936126, 2023). "DCN, which is a polysaccharide-protein of the ECM, binds to cell surface receptors and mediates cancer suppression." (PMID 36993958, 2023). "There are also limited prognostic studies evaluating the role of decorin in humans with STS, although the ability for decorin to influence the behavior of human cancer has been reported in several in vitro and in vivo studies." (PMID 37104411, 2023). "A therapeutic model with the combination of oncolytic adenovirus carried decorin with a CAR-T targeting carbonic anhydrase IX (CAIX) has been reported to induce ECM remodeling and immunoreaction in cancer recently." (PMID 36906534, 2023). "The “Proteoglycans in cancer” pathway was also exclusively enriched in AA-SScL fibroblasts, driven by the upregulation of IGF2, DCN, LUM, COL1A1, COL1A2, and the receptors KDR and TLR4." (PMID 36835058, 2023). "APOB is necessary for the interaction between decorin (DCN) and collagen I, and decorin is required for collagen fiber orientation, which is crucial for cancer metastasis." (PMID 36428687, 2022). "These two targets have a few interacting proteins in common such as TIMP (1, 2 and 3), STAT 3, VEGF A, SRC, DCN, MMP 10 and CD 44 and all are supposed to be plum targets for cancer therapies." (PMID 34075089, 2021). "Similar to TSKU, decorin (DCN) and biglycan (BGN) are two key SLRPs that have altered expression in various cancers with diverse clinical outcomes, and BGN serves as a potential marker of cancer proliferation associated with poor clinical outcome." (PMID 33428594, 2021). "DCN, BGN, LUM and fibromodulin (FMOD) are the most reported members of SLRPs involved in cancer progression." (PMID 34888227, 2021). "For the case of fibroblast cells associated dataset, the most significant pathway obtained was Proteoglycans in cancer (p value 1.2 × 10−3) (CD63, DDX5, DCN, LUM, ITGB1)." (PMID 34071236, 2021).
cancer (continued). "Decorin, a prototype member of the SLRP family, has gained recognition for its essential roles in multiple pathologies including cancer." (PMID 32824864, 2020). "ECM proteins Laminin-5, Tenascin-C, and Decorin bind EGFR to regulate its activation and function in cancers." (PMID 32719793, 2020). "Decorin is a proinflammatory ECM protein and its binding network has been summarized; decorin reduces IL-10 levels via micro-21 and protocadherin alpha gene cluster (PCDA) 4 in cancer cells." (PMID 33193379, 2020). "Targeting RGS4 likewise diminished the expression of decorin, an extracellular matrix (ECM) protein engaged in the cell growth, differentiation, proliferation, adhesion and metastasis of various cancers." (PMID 32392739, 2020). "In cancers, ECM proteins like Perlecan, Versican, Aggrecan, Decorin and Biglycan all bind growth factors to support pro-tumorigenic as well as anti-tumorigenic effects." (PMID 32719793, 2020). "DCN (decorin) is a small leucine reach proteoglycan, a part of ECM that binds to collagens and plays an important role in cancer development and metastasis." (PMID 32283808, 2020). "We found two genes, DCN and SPP1, showing different expression in AEM compared to either AEC or advanced carcinoma." (PMID 33322258, 2020). "Statistical significance was found when comparing expression of DCN and SPP1 in AEM and advanced carcinoma (p < 0.001 in both cases)." (PMID 33322258, 2020). "Decorin (DCN) was known as an extracellular protein and a pan-RTK inhibitor, which participates in cancer cell growth, spread, proinflammatory processes, and antifibrillogenesis." (PMID 31583243, 2019). "At 200 MOI, dE1/GFP/DCN completely suppressed TGF-β expression, implying that Ad-mediated DCN expression can efficiently inhibit TGF-β production in cancer cells." (PMID 28002796, 2017). "The lungs are an organ with a large amount of interstitial matrix and we have shown that patients with fibrotic lung disorders, such as cancer and IPF, have an increased level of degraded decorin." (PMID 28793886, 2017). "The results of the present study favor the use of ECM macromolecules such as decorin in order to orchestrate, reengineer, reprogram, or normalize the structure and composition of the TME to achieve a less friendly environment for the cancer cells." (PMID 28653173, 2017). "In many tumors the cancer-specific matrix also includes increased ASPN and DCN, due to their induction by e.g. TGFβ or stiff matrix." (PMID 29176937, 2017). "The 95 % confidence intervals of the hazard ratios of P4HA3, SRPX2, DCN, OMD, and TCF4 all excluded 1 in multivariate analysis in both cancer sets." (PMID 27809802, 2016). "In contrast, DCN (chr12q21.33), LIFR (chr5p13.1), ABCA8 (chr17q24.2), C7 (chr5p13.1) and ZEB2 (chr2q22.3) on predicted PCSRs were down-expressed in 9, 7, 8, 8 and 8 cancers, respectively." (PMID 24796549, 2014). "Of the 990 cases 928 (94%), 967 (98%) and 930 (94%) were interpretable for DCN staining in stroma, DCN staining in the carcinoma and HSP90B1 staining in the carcinoma, respectively." (PMID 22363530, 2012). "In conclusion, we detected significant under-expression of genes SLC26A3, TPM1, DCN and CALM3 in CRC, providing further evidence of their decreased mRNA expression and thus implicating them in the development of this type of cancer." (PMID 19678923, 2009). "Similarly, ferroptotic cancer cells, including HT-1080, PANC-1, HeLa, and KPC lines, have been observed to release the proteoglycan decorin (DCN), which interacts with the AGER receptor on macrophages." (PMID 38844964, 2024). "Decorin is secreted from normal fibroblasts, and this cytokine has non-cell-autonomous anti-cancer effects." (PMID 38667295, 2024).